TBXAS1 (thromboxane A synthase 1)
Diseases named in the same sentence as TBXAS1 in open-access papers (continued):
Sharing a sentence is not in itself a finding about the gene and the disease.
osteosarcoma (1 paper, 2024). A usually aggressive malignant bone-forming mesenchymal neoplasm, predominantly affecting adolescents and young adults. "In addition, single-cell data analysis showed that the platelet-related gene TBXAS1 is mainly enriched in macrophages, and markers of macrophages are significantly associated with poor prognosis in osteosarcoma patients." (PMID 39720182, 2024). "Additionally, we found that the platelet-related gene TBXAS1 is a key pathogenic gene in osteosarcoma, and its interaction with macrophages may be one of the reasons why platelet-related genes promote the progression of osteosarcoma." (PMID 39720182, 2024). "In summary, this article used the largest osteosarcoma single-cell data to date to discover that TBXAS1 is a key platelet-related gene leading to poor prognosis in osteosarcoma, filling the gap in the potential role of platelet activity genes in osteosarcoma." (PMID 39720182, 2024). "This study identified TBXAS1 as a key platelet-related gene responsible for the poor prognosis of osteosarcoma through bioinformatics methods." (PMID 39720182, 2024). "Among these, TBXAS1 was identified as a key gene that affects the prognosis of osteosarcoma patients." (PMID 39720182, 2024). "This article integrates single-cell and bulk RNA data to validate the promotional effect of platelets on osteosarcoma and discovers that the possible interaction between the platelet-related gene TBXAS1 and macrophages is a potential mechanism of platelet pro-tumor effects." (PMID 39720182, 2024). "Moreover, the functional properties of TBXAS1 position it as a promising therapeutic target for future osteosarcoma treatments." (PMID 39720182, 2024). "TBXAS1 is a key platelet-related gene that leads to poor prognosis in osteosarcoma, and this gene may affect the prognosis of osteosarcoma patients by interacting with macrophages." (PMID 39720182, 2024). "To verify the effect of TBXAS1 gene on immunotherapy, we entered the gene expression matrix data into TIDE website to calculate TIDE score, and the results showed that more patients with osteosarcoma with high TBXAS1 expression had a response to immunotherapy than those with low TBXAS1 expression." (PMID 39720182, 2024). "Consequently, this study advocates for further experimental investigations to elucidate the mechanistic role of TBXAS1 in osteosarcoma progression and to explore its feasibility as a novel therapeutic target." (PMID 39720182, 2024).
pancreatic ductal adenocarcinoma (1 paper, 2022). An infiltrating adenocarcinoma that arises from the epithelial cells of the pancreas. "In patient samples, we identified a transition from PGD2- to PGE2-producing enzymes in the epithelium during the transition to pancreatic ductal adenocarcinoma, fibroblast/tumor expression of PTGIS, and myeloid/tumor cell expression of TBXAS1." (PMID 36277993, 2022).
preeclampsia (1 paper, 2013). Preeclampsia is a hypertensive disorder of pregnancy that is characterized by new-onset hypertension with proteinuria presenting after 20 weeks of gestation, and depending on mild or severe forms may initially present with severe headache, visual disturbances, and hyperreflexia. "In addition to its role in several pathophysiological processes including hemostasis, recent research suggested a role for TBXAS1 in several cancers as well as preeclampsia." (PMID 23766848, 2013).
Primary amenorrhea (1 paper, 2015). "The gene TBXAS1, which encodes thromboxane synthase involved in platelet aggregation and clotting, may be of interest given that our patient has two menstrual cycles a month, and two other patients with deletions spanning the 7q33 to 7q36 region have had the opposite phenotype of primary amenorrhea." (PMID 26064708, 2015).
renal carcinoma (1 paper, 2024). A carcinoma arising from the epithelium of the renal parenchyma or the renal pelvis. "RCC also demonstrates upregulation of ALOX5, TBXAS1, and cysLTR1, supporting literature on the role of TBXA2 in upregulating renal cancer and 5-LOX in progressing carcinogenesis." (PMID 39062733, 2024).
schizophrenia (1 paper, 2013). A major psychotic disorder characterized by abnormalities in the perception or expression of reality. "The association identified in present study suggested evidence that areas of three genes (TBXAS1, PIK3C2G and HS3ST5) or related chromosome regions harbor susceptibility allele for schizophrenia with GM volume as QT." (PMID 24086445, 2013).
cancer (15 papers, 2005 to 2025). A tumor composed of atypical neoplastic, often pleomorphic cells that invade other tissues. "Mutation of TBXAS1 in this pan-cancer panel is, philosophically, quite different." (PMID 36234768, 2022). "An example of this is TBXAS1, whose expression is increased in nine types of cancer but decreased in another four types of cancer." (PMID 36765904, 2023). "What was not previously apparent is the high degree of correlation between TBXA2R and TBXAS1 expression across all tumors in the TCGA pan-cancer dataset (Pearson co-efficient 0.58; p < 0.0001)." (PMID 36234768, 2022). "This confusion becomes more apparent when assessing the TCGA pan-cancer dataset for correlations between TBXAS1 expression and clinical outcomes." (PMID 36234768, 2022). "Like TP expression, The Cancer Cell Line Encyclopedia suggests the addition of cancers with significant TBXAS1 expression that are currently uncharacterized, including ALL, AML, CML, and renal cancer." (PMID 36234768, 2022). "This indicates that metabolites generated by TBXAS1 may play a very different role in cancer to that of TBXA2R." (PMID 16250911, 2005). "For example, “don’t eat me” signal expression was either no change or mildly increased in Met1 cells but significantly increased in Met2 cells such as Cd274 (PD-L1), Cd52, and Tbxas1, indicating that these genes may play a significant role in immune evasion of metastatic cancer cells." (PMID 40458726, 2025). "Finally, four novel enzymes with unappreciated biological functions in cancer were identified, namely thromboxane A synthase 1 (TBXAS1), 5′,3′‐nucleotidase, cytosolic (NT5C), glycosyltransferase 8 domain containing 2 (GLT8D2) and reticulon 4 interacting protein 1 (RTN4IP1)." (PMID 39757767, 2025). "This suggests that TBXAS1 may play a role in promoting tumor development in most cancers." (PMID 39720182, 2024). "Recently, multiple studies have indicated functional roles for both TBXAS1 and TP in the essential processes of neoplastic transformation including enhanced tumor cell motility and invasion, proliferation, and therapeutic resistance that are critical steps in cancer progression." (PMID 36234768, 2022). "However, in NSCLC and small-cell lung cancer cells, TXA2S expression is regulated by NF-κB, suggesting unrecognized transcription factors may play a role in regulating TBXAS1 transcription in cancer." (PMID 36234768, 2022). "Moreover, knockdown of TBXAS1 or TXA2R lowered the rate of cancer cell proliferation." (PMID 29872696, 2017). "TBXAS1 inhibitors induce apoptosis and inhibit the migration and proliferation of GBM cancer cells, indicating an autocrine effect of TxA2." (PMID 36765904, 2023). "Strictly speaking, Tbxas1 is not a “don’t eat me’ signal”, but it indirectly helps cancer cells evade immune elimination via platelet activation and aggregation." (PMID 40458726, 2025).
tumor (13 papers, 2005 to 2025). "While TBXA2R is highly expressed in aggressive tumours and linked with poor prognosis, TBXAS1 is expressed at significantly low levels in high grade tumours and tumour patients with poor prognosis." (PMID 16250911, 2005). "In the arachidonic acid cascade, TBXAS1 encodes for thromboxane synthase, which converts prostaglandin H2 into thromboxane A2, a process that involves the modulation of cell cytotoxicity and tumor growth and metastasis." (PMID 36466837, 2022). "First, we found that TBXAS1 gene was significantly differentially expressed in nine tumors, of which seven tumors showed significantly increased TBXAS1 expression in tumor tissues, and the other two tumors showed decreased expression." (PMID 39720182, 2024). "Tumor cells express synthases TBXAS1 (TXA2, TXB2, 12-HHTre) and CYP2S1 (12-HHTre), and some subclusters are enriched for PGE2 synthase PTGES or prostacyclin synthase PTGIS." (PMID 36277993, 2022). "The thromboxane (TxA2, TxB2) and 12-HHTre synthase Tbxas1 is detected in macrophages, while 12-HHTre synthase Cyp2s1 is expressed in PanIN and tumor cells." (PMID 36277993, 2022). "Analyses of PDAC are largely in agreement with observations made from the Elyada et al41 data set, including expression of PGE2 synthases in tumor cells, Ptgis in fibroblasts, and Tbxas1 in macrophages/myeloid cells (Figure A2)." (PMID 36277993, 2022). "Within the same tissue sections, TBXAS1 staining was localized mainly in tumor cells instead of stromal cells." (PMID 29872696, 2017). "While TBXA2R is commonly expressed in tumours and particularly in aggressive tumours, TBXAS1, in contrast, showed a very different expression pattern from that of TBXA2R." (PMID 16250911, 2005). "While TBXA2R is normally expressed in tumours and particularly in aggressive tumours, TBXAS1, however, showed a very different expression pattern from that of TBXA2R." (PMID 16250911, 2005). "TBXAS1 is expressed at significantly low levels in high grade tumours (grade 3) and in patients with predicted poor clinical outcome (prognostic index NPI greater than 5.4)." (PMID 16250911, 2005). "In the current study, we have observed that there was significant correlation between levels of TBXA2R and TBXAS1 and tumour grade." (PMID 16250911, 2005). "Moreover, 4T1 tumor cell invasion ability was increased by overexpression of TBXAS1, whereas it was ameliorated by aspirin, indomethacin, or SC560 treatment." (PMID 29872696, 2017). "Grade 3 tumour had significantly lower levels of TBXAS1 compared with grade 1 tumours (p = 0.026)." (PMID 16250911, 2005). "The levels of TBXAS1 transcript were identical between normal and tumour tissues." (PMID 16250911, 2005). "However, TBXA2R expression was significantly increased in grade 3 tumours(p = 0.006 vs grade 1), while TBXAS1 was significantly reduced in grade 3 tumours (p = 0.026 vs grade 1 tumours)." (PMID 16250911, 2005). "Moreover, research suggests TAM-EVs could influence lipid metabolism in cancer cells, shifting from a COX2/PGES pathway that promotes tumor growth to a COX1/TBXAS1 pathway, potentially curtailing the tumor-supporting effects of certain prostaglandins." (PMID 40485727, 2025). "Hence, low levels of TBXAS1 could favor tumor escape from anti-tumor immunity and may also support PMN-MDSC suppressive functions." (PMID 33312958, 2020). "Additionally, it has been reported that TBXAS1 protein is significantly enriched in TAM exosomes, and its expression is related to tumor progression." (PMID 39720182, 2024). "Furthermore, it was also reported that the TBXAS1 protein was significantly enriched in TAM exosomes, and its expression was correlated with tumor progression." (PMID 36275756, 2022). "Furthermore, Cathcart and colleagues observed no prognostic role for TBXAS1 in NSCLC, despite significant elevations in TBXAS1 (and TXB2) levels in tumor tissues than the matched “normal” tissues." (PMID 36234768, 2022).
tumor (continued). "TBXAS1 is expressed in both CD68 + macrophages and the tumor epithelium." (PMID 36277993, 2022). "A similar differential expression pattern was seen in tumours from patients with different prognosis, in that patients with predicted poor prognosis had higher, but not statistically different, levels of TBXA2R, and significantly lower levels of TBXAS1 (p = 0.008)." (PMID 16250911, 2005). "EPA also slightly reduced TBXAS1 expression both in the MMTV-neu mammary gland and tumor, but the difference was not statistically significant." (PMID 29872696, 2017).
cardiovascular disease (5 papers, 2017 to 2024). "The TBXAS1 enzyme is involved in several pathophysiological processes, including hemostasis, cardiovascular disease, and apoplexy." (PMID 38271973, 2024).
infection (4 papers, 2016 to 2023). The state of being infected such as from the introduction of a foreign agent such as serum, vaccine, antigenic substance or organism. "Several genes were significantly upregulated (Pla2g4a, Pla2g4c, Pla2g7, Ptgs1, Ptgs2, Pla1, Tbxas1) or downregulated (Alox5, Pla2g2d, Pla2g1b, Pla2g4b, Pla2g4f) during infection." (PMID 35812400, 2022).
skeletal dysplasia (2 papers, 2011 to 2025). Any Mendelian diseases that affects growth and development of the skeleton. "Ghoshal hematodiaphyseal dysplasia (GHD) is an extremely rare autosomal recessive disorder caused by pathogenic variants in the TBXAS1 gene, leading to bone marrow fibrosis, transfusion-dependent anemia, and skeletal dysplasia." (PMID 41561227, 2025).
colonic polyps (1 paper, 2015). "Our immunohistochemistry staining results clearly showed that both TBXA2R and TBXAS1 were highly expressed in most colonic polyps or tumors, but not in normal colorectal tissues." (PMID 25750933, 2015).
TBXAS1 also shares sentences with these, for which no sentence is quoted: atherosclerosis (3 papers); adenocarcinoma (2); cerebral infarction (2); deep vein thrombosis (2); endothelial dysfunction (2); glioma (2); Hypertension (2); pulmonary arterial hypertension (2); acute myeloid leukemia (1); anemia (1); brain cancer (1); calcification (1); chronic myelogenous leukemia (1); colitis (1); colon adenocarcinoma (1); COVID-19 (1); esophageal cancer (1); gallbladder adenocarcinoma (1); gastric ulcer (1); Glanzmann thrombasthenia (1); hepatocellular carcinoma (1); intestinal polyp (1); liver cancer (1); lymphoma (1); mastitis (1); mesothelioma (1); metabolic disorders (1); metabolic syndrome (1); myocardial ischemia (1); non-small cell lung carcinoma (1).
A further 7 diseases each share a sentence with TBXAS1 in 1 paper.